STAT1 (signal transducer and activator of transcription 1)
Diseases named in the same sentence as STAT1 in open-access papers (continued):
Sharing a sentence is not in itself a finding about the gene and the disease.
tumor (continued). "Taken together, our data suggests a link between high STAT1 levels and immune evasion, which supports in turn that STAT1 is an immune-tumor promoter in MSI-H CRC, but not in MSS CRC." (PMID 32641473, 2020). "3.3, we show the nodes having high role A and B motif centrality, such as HIFs, HDAC, BRCA1, EGR1, STAT1, GATA1 and GATA3, and also report their functions as master regulators in liver function, cell proliferation, tumor suppression and genomic stability, etc. as well as stress response." (PMID 32541819, 2020). "RT2.Stat1+/+-cancers and RT2.Stat1−/−-cancers had normal baseline levels of PD-L1 and β2-microglobulin, and in RT2.Stat1−/−-cancers β2-microglobulin was in the tumour microenvironment." (PMID 32165639, 2020). "Our results showed that Stat1 ablation and corresponding loss of IDO1+ tumor cells did not affect nuclear β-catenin levels in sporadic ApcMin tumors." (PMID 32444775, 2020). "IFN-γ is involved in anti-viral and anti-tumor immune responses by triggering transcription of several genes such as Ido-1 which is transcriptionally regulated by IFN-γ through activation of Jak-1 and STAT-1 but also NF-κB." (PMID 32384638, 2020). "In contrast to the tumor-promoting function of STAT3, there are indications that STAT1 might have rather tumor-suppressive effects." (PMID 31683891, 2019). "This study identifies dual functions for caspase-11 during CAC—generating IL-1β via the non-canonical inflammasome; and mediating the tumour suppressor activities of STAT1." (PMID 30538296, 2019). "In addition, PDL1 mRNA, p-Stat1 and PD1 expression were elevated after IFNα treatment in the xenograft tumours." (PMID 30555157, 2019). "The tyrosine phosphorylation of STAT1 and STAT3 are catalyzed by Janus kinase (JAK) and control the STAT1 and 3 downstream transcriptome, including the TGF-B1 and TNF gene network, and promote tumor progression and chemoresistance in cancer cells." (PMID 31182137, 2019). "We elucidated that KHSRP could interact with HNRNPC and HNRNPC-mediated tumor growth and metastasis could be, at least partly, attributed to the activation of IFN-α-JAK-p-STAT1 signaling pathway, which is critical for tumorigenesis and metastasis in NSCLC." (PMID 31775888, 2019). "In order to investigate STAT1 expression in HCC patients, we first searched the online datasets from Oncomine and GEO Datasets (GSE 14520), including six cohorts of 671 HCC tumor tissues with 585 tumor-free liver tissues." (PMID 30456450, 2019). "We found that u-STAT1 is significantly elevated in patient HCC tumor tissues and predominantly expressed in cytoplasm; while p-STAT1 is absent." (PMID 30456450, 2019). "Transient overexpression of STAT1-wt in B16F10 tumor cells that were cultured in OGD conditions led to strong increase in STAT1 protein levels, but failed to restore MHC-I expression." (PMID 31196219, 2019). "Some evidence in the literature suggests that STAT1 may be an oncogenic molecule in MYC-independent MB tumors, while other studies show how STAT1 activation induces anti-tumor effects in MYC-independent MB." (PMID 31382461, 2019). "Surprisingly, we did not observe positive staining for p-STAT1 in both tumor and tumor-free tissues." (PMID 30456450, 2019). "Collectively, our data demonstrate that caspase-11, and a functional non-canonical inflammasome, is required for the tumour suppressive role of STAT1 during experimental CAC." (PMID 30538296, 2019). "STAT1 protein mainly function as tumor suppressor, suggesting that not all STAT proteins participate in the progression of inflammation and malignancy in human." (PMID 30847297, 2019). "Some studies find that JAK inhibition suppresses tumor growth, while other studies find that they ultimately enhance metastasis, likely because they also suppress the positive influence of JAK activity on other STAT proteins (including STAT5 and STAT1/2 )." (PMID 31684144, 2019).
tumor (continued). "Interestingly, the class I HDACi has been shown to inhibit iNOS, COX2, and arginase-1 in the MDSCs of tumor-bearing animals, in addition to enhancing the effectiveness of PD-1 inhibition to abrogate lung and renal tumor formation, which might be a product of STAT1 pathway inhibition." (PMID 31842362, 2019). "In our experimental model, in the absence of STAT1, tumor appearance was faster, suggesting a favorable microenvironment for tumor development." (PMID 30235866, 2018). "STAT1 activation was not prominent, and only a few tumor cells stained positive for pY‐STAT1 in STAT1flox/flox mice." (PMID 29419930, 2018). "STAT1 has been shown to mediate the anti-proliferative effect of IFN-γ on tumor cells, and STAT1 is an important mediator for antiangiogenic signals, and inhibits tumor growth and metastasis of RAD-105 cells in vivo." (PMID 30235866, 2018). "It has to be shown if tumor cell‐intrinsic STAT1 is responsible for this sex‐specific effect because bulk gene expression data do not discriminate between tumor and stromal cells." (PMID 29419930, 2018). "Tumor cell‐intrinsic cytoplasmic STAT1 was not identified as prognostic factor after sex stratification but there was a trend toward favorable prognosis in male patients." (PMID 29419930, 2018). "In our model, the increase in tissue damage and inflammation in STAT1−/− CAC-induced mice, particularly in the initial steps of tumor development, indicates that another source of inflammation is induced when STAT1 is not present." (PMID 30235866, 2018). "STAT1 plays an important role in bone growth and bone formation, which suggests that STAT1 might be involved in the development of GCT, especially tumor invasiveness." (PMID 29651441, 2018). "An oncogenic function was suggested in SOCS1 knockout mice, which developed sporadic CRC with strong tumor cell‐intrinsic STAT1 activation, but otherwise, ApcMin‐induced intestinal tumorigenesis was not affected in STAT1 knockout mice." (PMID 29419930, 2018). "STAT1 is known to be activated by signaling from INFs, and advanced studies on the development of JAK/STAT inhibitors have found that expression of the STAT1 pathway confers cellular resistance to DNA-damaging agents and supports tumor growth." (PMID 30453645, 2018). "We found that SLE altered the expressions of some genes related to tumor immune evasion (e.g. IL-6, IL-17, STAT1, TNF-α, CD45, MHCII) (Data not shown)." (PMID 28596565, 2017). "Although the specific contributions of STAT1 to vSCC progression have not been fully elucidated, it is clear that this protein is important in tumor-initiated immune responses." (PMID 29225558, 2017). "This process is downregulated in the tumour environment due to lack of IFNγ-induced STAT1 signalling." (PMID 28315228, 2017). "Emerging STAT3-null tumours re-established immune suppression based on the absence of a robust Granzyme B+ response and impaired nuclear STAT1 translocation." (PMID 28276425, 2017). "In summary, our results are consistent with a model that suggests that the ratio of STAT1 to STAT3 expression (without the necessity of STAT1 tyrosine phosphorylation) dictates CRC tumor growth." (PMID 27191495, 2016). "Also, commensurate with their role in regulating cytokine-dependent inflammation and immunity, the relationship between STAT1 and STAT3 and components of tumour microenvironment is unclear." (PMID 27769057, 2016). "Moreover, the cell-intrinsic STING/IFN/STAT1 pathway triggers a typical ISG fingerprint that ultimately contributes to resistance to treatment and favors tumor cell re-growth." (PMID 27791205, 2016). "The present results suggest that STAT1 and STAT3 may affect disease outcome through direct impact on tumour cells, counteracting aggressive tumour features, as well as interaction with the surrounding microenvironment." (PMID 27769057, 2016).
tumor (continued). "However, the fact that OSM induces the phosphorylation and activation of both STAT1 and STAT3 and yet still presented anti-tumor effects poses a paradox why LAC cells selectively response to activated STAT1 and ignore the pro-oncogenic STAT3." (PMID 27486982, 2016). "Furthermore, increased expression of a subset of ISGs, including IFITM1, EIF2AK2, STAT1, and IFI27, has been reported in several types of cancers, and these ISGs have been shown to promote tumor growth and resistance to chemotherapy and radiotherapy." (PMID 26897526, 2016). "IFN-α treatment alone upregulated the tyrosine phosphorylation of STAT1 in tumor tissues compared with the control group, and the combination treatment of IFN-α plus emodin further promoted the phosphorylation of STAT1 compared with that of IFN-α treatment alone." (PMID 26683360, 2016). "RNA-seq analysis of tumor xenografts revealed that C188-9 modulated many STAT3-regulated genes involved in oncogenesis, as well as genes involved in chemoresistance and radioresistance that previously were shown to be regulated by STAT3 and STAT1." (PMID 27027445, 2016). "In the present study, increased tumour cell expression of both ph-STAT1 and ph-STAT3 was associated with improved survival and the phenotypic characteristics of the tumour, in particular the low tumour grade and lack of tumour necrosis." (PMID 27769057, 2016). "Not surprisingly, therefore, deletion of STAT1 results in impaired NK cytolytic activity in vitro and reduced tumor rejection in vivo, despite normal numbers of NK cells, whereas STAT5-deficient mice lack NK cells completely." (PMID 27148271, 2016). "Furthermore, in tumor cell lines, STAT3 promoted proliferation and cell survival, while STAT1 was antiproliferative and pro‐apoptotic." (PMID 26931423, 2016). "STAT1 and STAT3 are commonly considered to have opposing effects, where STAT1 have tumor suppressor properties and STAT3 may act as an oncogene." (PMID 27036022, 2016). "Thus, we conclude that a higher ratio of STAT1/STAT3 expression was accompanied by better prognosis and slower xenograft growth, with smaller tumor size." (PMID 27191495, 2016). "The median survival of patients showing neither STAT1 nor STAT3 activity (nuclear) in their tumor specimens was at least 33 months shorter in comparison to patients with tumor related activation of STAT1, STAT3 or both proteins." (PMID 27191495, 2016). "The present study reports for the first time a negative association between ph-STAT1 and ph-STAT3 expression and tumour necrosis." (PMID 27769057, 2016). "However, STAT1 can also be activated by other stimuli such as IL6 and IL10, which play crucial roles in tumor survival and progression." (PMID 26654227, 2015). "Serum IL-6, through p-STAT3 rather than p-STAT1 signal pathway, affected hepatic function, tumor progression, and determine HCC patient survival." (PMID 25908103, 2015). "Accordingly, we observed a significant increase in STAT1 and STAT2 signaling in survivin-specific T cells upon coculture with CCR9lo MCF7 cells, suggesting that anti-tumor type-1 immune response is impeded by tumor-specific CCR9 (Fig5D and E)." (PMID 25691366, 2015). "After labeling IFIT3 with the STrEP Tag, protein complexes that formed after interaction of IFIT3-StrEP with proteins from the tumor cell lysate stained positive for JNK and STAT1 by Western Blot analysis, while other typical signaling proteins such as Akt, EGFR, MAPK and Src were not detectable." (PMID 25650658, 2015). "In marked contrast, myofibroblasts isolated from a CD patient, which failed to activate STAT1 signaling in tumor cells, had lost the ability to inhibit the growth of tumor cells." (PMID 24818101, 2014). "STAT1 knockout mice have increased tumor incidence, presumably because of a lack of immune surveillance since STAT1 induces IL-12 expression and helps shape a Th1-IFN-γ immune response in collaboration with NF-κB." (PMID 24762633, 2014).
tumor (continued). "Indeed, STAT1, a major transcriptional activator of IDO in myeloid cells, also potently induces IDO transcription in tumor cells when activated constitutively or after stimulation with IFN-g." (PMID 24657910, 2014). "We evaluated whether the classical signaling pathways of IFN-γ (STAT1) and IL-13 (STAT6) were activated in tumor cells following culture in activated lymphocyte-conditioned medium." (PMID 24911872, 2014). "Since ZOL reportedly radiosensitizes various tumor cells, STAT1 downregulation may be a common cellular response to ZOL in those overexpressing STAT1." (PMID 23741352, 2013). "Our results indicate Stat1 and Stat2 show differential activities between tumor and normal breast epithelium samples." (PMID 23885756, 2013). "The lack of Stat1 results in aberrant response to IFN signaling and makes the tissue more susceptible to tumor development." (PMID 23885756, 2013). "A mutant form of STAT1 lacking the functionally critical Tyr 701 residue is defective in this function, suggesting that STAT1 suppresses tumor formation by regulating the transcription of its target genes." (PMID 22264274, 2012). "These were sufficient to design a new discriminating hpdODN that inhibits STAT3 and not STAT1, thereby inducing tumor cell death without interfering with STAT1-dependent processes." (PMID 22423663, 2012). "Although experimental validation is needed, the tumor suppressors/pro-apoptotic factors, MZF1 and the ubiquitous transcription factor STAT1 may be biologically relevant as decreased binding interactions might lower SP140 expression." (PMID 22235315, 2012). "We show that high levels of IFN-γ are produced during aATC-mediated targeted killing of tumor cells, thus we reasoned that IFN-γ may induce apoptosis by inhibiting Stat3 phosphorylation and inducing Stat1 phosphorylation." (PMID 23185240, 2012). "This inhibitor was designed to block Stat3 but not Stat1 function, thereby presumably avoiding the tumor antagonist effects of Stat1." (PMID 22838736, 2012). "Although the S1N mice exhibited a shorter latency than the 129S6/SvEv STAT1-/- mice, the penetrance of the two cohorts was indistinguishable and the difference in the overall tumor incidences was not statistically significant (P = 0.26)." (PMID 22264274, 2012). "In contrast, IFNγ/STAT1 signaling and autophagy are not activated in tumor cells from the lungs of therapeutically treated mice." (PMID 21931823, 2011). "The critical effect of STAT1 is not restricted to any distinct tumor type but is of global relevance." (PMID 22185785, 2011). "Pyk2, MDR1, GAGE1, MAP7 and STAT1 were found to be overexpressed in more than 60% of the tumor liver tissues compared to the adjacent non-tumor liver tissues (*p<0.05)." (PMID 22096562, 2011). "Since many cytokines act via homologous STAT proteins (e.g. STAT1), it was imperative to test whether FLLL32 had deleterious effects on the action of cytokines that might promote an anti-tumor response." (PMID 20576164, 2010). "Western blotting analysis revealed that STAT1 is quickly activated in tumor cell-stimulated CTLs, but not in CD3 mAb-stimulated CTLs." (PMID 21124930, 2010). "STAT1H tumor cells also demonstrate resistance to IFN-gamma (IFNγ), ionizing radiation (IR), and doxorubicin relative to parental B16F1 and low expressors of the IFN/STAT1 pathway (STAT1L genotype)." (PMID 19503789, 2009). "The GG pathway demonstrated the greatest protection from IR-induced suppression and showed no significant change in STAT1 WT tumours." (PMID 19891767, 2009). "STAT1, the first described member of the STAT transcription factor family, is the master transcription factor for IFN-related intracellular signaling and therefore tumor suppression related to IFNs." (PMID 19503789, 2009). "Our previous and current data suggest that targeting Stat1, IL6 and IL8 may enhance the therapeutic ratio for treatment of Stat1 over-expressing tumours." (PMID 19437244, 2009).
tumor (continued). "We observed an increase in STAT3, but not STAT1 (not shown), activity in tumor cells-monocyte co-cultures, as compared to each cell type cultured individually." (PMID 19718269, 2009). "We also showed that IR can directly activate the Stat1 pathway and that selection of parental interferon/radiosensitive tumours-SCC61 against in-terferons leads to the selection of clones that are cross-resistant to IR and IFN and over-express genes in the Stat1 pathway." (PMID 19437244, 2009). "Importantly, we previously reported that MCL1, IFITM1, and USP18 are co-expressed with STAT1 in the IR- and IFN-resistant nu61 tumor." (PMID 19503789, 2009). "However, constitutively activated STATs, especially STAT1, STAT3 and STAT5, have been found in a variety of human tumours and cancer cell lines, including blood malignancies and solid tumours." (PMID 12865928, 2003). "In contrast, most of the specimens showed no intranuclear staining of STAT1 protein in tumour cells." (PMID 12865928, 2003). "STAT1 deficiency has also been found in a variety of tumour cell lines and this deficiency is responsible for the lack of INF-γ-mediated tumour suppression effects." (PMID 12865928, 2003). "Analysis of primary tumours and cell lines indicated that the transcription factor STAT-1 is not constitutively phosphorylated/activated in TGCT." (PMID 12942126, 2003). "Moreover, VPS34 shapes the tumor microenvironment (TME) through its influence on both immune and cancer cells by modulating autophagy, cGAS-STING (cyclic GMP-AMP synthase Stimulator of Interferon Genes), and STAT1 pathways." (PMID 41972724, 2026). "Specifically, the activation of the STAT1 pathway induces M1 polarization of macrophages, exerting inflammatory functions and cytotoxic effects, whereas the activation of the STAT2 pathway mediates M2 polarization of macrophages, inhibiting tumor immunity and promoting the progression of GC." (PMID 40858547, 2025). "We also observed that tumor cells that engaged senescence-related transcriptional programs, or “Sen-High” cells, upregulated IFN-γ signaling machinery, including Ifngr1, Ifngr2, Jak1, Jak2, Irf1, and Stat1, as well as IFN-γ target genes Cxcl9, Cxcl10, and Tap1." (PMID 40299790, 2025). "IFI27 is transcribed as a type I interferon (IFN-I) stimulated gene (ISG) mediated by the STAT1/STAT2/IRF9 complex, and activation of the interferon-alpha receptor and increased mRNA levels of ligands and receptors in the TGFB pathway play important roles in the PDAC tumor microenvironment." (PMID 41008826, 2025). "Treatment of IFN-α alone upregulated the tyrosine phosphorylation of STAT1 in tumor tissues compared with the control group and aspirin group and the combination treatment of IFN-α plus aspirin further enhanced the phosphorylation of STAT1 compared with that of IFN-α treatment alone." (PMID 39826687, 2025). "In addition, tumor cells displayed serine phosphorylation at position 727 in both STAT1 and STAT3, as determined by immunostaining with phospho-serine-specific antibodies directed against STAT1 and STAT3, respectively." (PMID 40287766, 2025). "To evaluate whether STAT1 Lys637 acetylation could serve as a predictive biomarker for ICB response independent of prior cetuximab exposure, we analyzed an independent cohort of cancer patients with tumor samples collected before ICB treatment." (PMID 41205596, 2025). "Failing to provide additional protection against cisplatin toxicity after knockdown of the STAT1 gene in mice; EGCG reduced cisplatin-induced ROS generation and ERK1/2 and STAT1 activity, but retained STAT3 and Bcl-xL activity, allowing cisplatin to continue its anti-tumour effects." (PMID 40351440, 2025). "STAT1 is also considered a negative transcription factor that suppresses tumor angiogenesis." (PMID 40370455, 2025).